FASN (fatty acid synthase)
Diseases named in the same sentence as FASN in open-access papers (continued):
Sharing a sentence is not in itself a finding about the gene and the disease.
Hepatic steatosis (continued). "Our data demonstrate that FASstatin decreased FASN protein expression and significantly reduced body and liver weights, hepatic steatosis, fibrosis, and inflammation, and serum ALT and AST activity." (PMID 38206764, 2024). "Using unbiased protein interactomics screening and molecular validation, we found that TRIM56 directly interacted with FASN, a key lipogenesis factor driving hepatic steatosis in NAFLD/NASH." (PMID 38206764, 2024). "Silymarin showed a decrease in liver malondialdehyde content, expression of FASN, TNFα, IL‐6, iNOS genes in liver and hepatic steatosis." (PMID 39324876, 2024). "AMPK can downregulate expression of FASN, impede hepatic intracellular aliphatic acid synthesis and saturation, and ameliorate fatty liver disease." (PMID 38813108, 2024). "Important to note is that increased CD36 and FASN expression has shown to be related to increased hepatic steatosis." (PMID 36946061, 2023). "GSK2879552 is an LSD1 inhibitor that showed beneficial effect to inhibit FASN expression and ameliorate hepatic steatosis in mice." (PMID 37834101, 2023). "Inhibition of the AMPK pathway promotes the transcription and translation of lipogenic genes, including fatty acid synthase (FASN) and encoding sterol regulatory element-binding protein 1 (SREBP1) within hepatocytes, finally promoting hepatic steatosis." (PMID 37371520, 2023). "The inhibition of fatty acid synthase (FASN), which is the enzyme that synthesizes palmitate from acetyl-CoA and malonyl-CoA, can suppress hepatic steatosis in a variety of mouse models of fatty liver disease." (PMID 36817797, 2023). "Previous studies have also shown increased PPAR-γ expression in mice that are fed a high-fat diet to induce hepatic steatosis.FASN is an essential enzyme that catalyzes the de novo synthesis of long-chain fatty acids." (PMID 38152126, 2023). "Recent studies have shown that inhibiting SREBP1, ACLY, ACSS2, ACACA, and FASN can improve fatty liver disease." (PMID 37065701, 2023). "A. argyi water extract also ameliorated hepatic steatosis by restricting lipogenesis via lowering the activities of fatty acid synthase and phosphatidic acid phosphatase." (PMID 36547081, 2022). "Hepatic FASN expression was reported to be significantly increased in vivo in a murine model of hepatic steatosis and correlated with the degree of hepatic steatosis in human NAFLD livers." (PMID 36012215, 2022). "Despite the minimal or no weight loss, physical exercise intervention in NAFLD patients has shown to reduce hepatic steatosis, probably due to reducing the lipogenic enzymes acetyl-Co-enzyme A carboxylase and fatty acid synthase, as seen in rodent studies." (PMID 36079070, 2022). "Both increased FASN and Kupfer cells have been shown to promote the development of liver steatosis, while the suppression of FASN and Kupfer cells can ameliorate alcohol-induced steatosis." (PMID 34306160, 2021). "It is known that AMPK activation directly phosphorylated ACC1 at serine 79 and suppressed its activity, and reduced FASN expression to attenuate fatty-acid-induced hepatic steatosis." (PMID 33806955, 2021). "This resulted in increased expression of sterol regulatory element-binding protein-1c (SREBP-1c), acetyl-coenzyme A carboxylase 1 (ACC1) and fatty acid synthase (FASN) and contributed to HCV-associated hepatic steatosis." (PMID 34066434, 2021). "In the WD/CCl4 murine model, the chronic treatment of PTM (10 mg/kg) for 13 weeks significantly reduced the protein level of FASN in the livers of treated mice, corroborating attenuated liver steatosis and reduced TG in their livers and plasma." (PMID 35052685, 2021). "We further determined that increases in the expression of FASN and PNPLA3 can cause increases in triglycerides levels, facilitate the detection of hepatic steatosis, and abolish IS." (PMID 33401717, 2021).
Hepatic steatosis (continued). "Vitamin D has been proven to protect against high-fat diet-induced fatty liver by acting on the expression of de novo lipogenesis-related genes, including FASN and Acaca, and fatty-acid oxidation-related genes such as the acetyl-coA oxidase (Acox)." (PMID 34067649, 2021). "This appears paradoxical because FASN suppression markedly improves steatosis in other experimental models of fatty liver, and FASN antagonists are under development as plausible treatments for hepatic steatosis." (PMID 34680405, 2021). "Previous studies showed that SREBP‐1c57 and SCD‐158 levels were up‐regulated in the fatty livers of NAFLD patients, and higher FASN levels were confirmed in human liver samples and the murine model of hepatic steatosis." (PMID 33400402, 2021). "Imipramine increases fatty liver scores and is linked to adipogenesis in the liver, including FABP4 and SREBP1 mRNA levels, in addition to adiponectin, FASN, and PNPLA3 activation." (PMID 34564583, 2021). "Taken together, these findings indicate that an alcohol-dependent decrease in MCD, FASN, and FASN-derived palmitic acid likely contributes to hepatic steatosis by decreasing mitochondrial FAO in the liver." (PMID 33013449, 2020). "Hepatic steatosis, inflammatory cell infiltration, and hepatocyte ballooning in the liver and increased hepatic mRNA expression of fatty acid synthase and glycerol-3-phosphate acyltransferase were observed in the MSG-treated mice." (PMID 32103741, 2020). "Increased FASN expression by OA was significantly attenuated by treatment with EAT or ECB in the hepatic steatosis model." (PMID 31170227, 2019). "An increase in ChREBP in HCV G1 infection is associated with maintaining insulin signalling sensitivity during fatty liver disease, induces expression of lipogenic enzyme acetyl-CoA carboxylase and fatty acid synthase genes." (PMID 31332246, 2019). "Celastrol also reduces the activity of FASN and alleviates hepatic steatosis during HCC development." (PMID 35539339, 2018). "Mice supplemented with palmitoleic acid exhibit higher fat deposition, hepatic steatosis, and increased hepatic expression of sterol regulatory element-binding protein 1c and fatty acid synthase, demonstrating the pro-lipogenic effect of this MUFA." (PMID 29471812, 2018). "Hyperinsulinemia and corruption of CEACAM1-mediated repression on hepatic fatty acid synthase (FASN) activity in hyperinsulinemia further support hepatic steatosis and SREBP1c-mediated lipogenesis and are accompanied by a reduction in hepatic β-oxidation." (PMID 30314283, 2018). "BBR treatment also decreased hepatic steatosis, as well as the expression of acetyl-CoA carboxylase and fatty acid synthase." (PMID 26936230, 2016). "The improvement of hepatic steatosis by linagliptin was also accompanied by a decrease in expression of fatty acid synthase." (PMID 27462372, 2016). "Expressions of fatty liver disease-related genes in liver were analyzed by qRT-PCR, in which FASN and CD36 were down-regulated according to the increasing dose of KIOM2012H in a similar way to HepG2 cells." (PMID 25849950, 2015). "We report here that the development of hepatic steatosis requires IL-1 signaling, which upregulates Fatty acid synthase to promote hepatic lipogenesis." (PMID 25216251, 2014). "Excessive iodine could induce oxidative stress and disturb thyroid hormone metabolism by upregulating mRNA expression for SREBP-1c and FAS (fatty acid synthase) in the liver, which plays a pivotal role in hepatic steatosis." (PMID 40431366, 2025). "It was also found that activated AMPK suppresses the expression of ACACA and FASN, which may reduce fatty acid synthesis, serum triglycerides, and cholesterol levels, thereby alleviating hepatic steatosis." (PMID 40176148, 2025).
Hepatic steatosis (continued). "Given that CIDEA is crucial for enhancing hepatic steatosis and has the ability to modulate the expression of essential genes involved in de novo fatty acid synthesis, namely, FASN and ACC, we delved deeper into how HLSP regulates AKT-driven lipid metabolism via CIDEA." (PMID 39958875, 2024). "All groups receiving silymarin showed a decrease in liver malondialdehyde content, expression of fatty acid synthase, tumour necrosis factor alpha, interleukin 6 (IL‐6) genes in the liver, and hepatic steatosis than the control, except those fed the PSM100 diet." (PMID 39324876, 2024). "PL may suppress lipogenic genes such as sterol regulatory element-binding protein 1c and fatty acid synthase in diet-induced hepatic steatosis." (PMID 38172797, 2024). "Therefore, γ-MCA functions to inhibit lipogenesis and related hepatic steatosis via the FXR/SHP/LXRα/FASN signaling." (PMID 36904254, 2023). "Moreover, whereas hepatic FASN ablation ameliorated hepatic steatosis and improved glucose tolerance in NCD-fed ob/ob mice to a greater extent than in Mc4r-KO mice, it also exacerbated both hyperglycemia in the fed state and liver dysfunction." (PMID 37681411, 2023). "The active phosphorylated form of FTY720/fingolimod, a prodrug treating multiple sclerosis, could reduce FASN expression by histone acetylation alteration, inhibit ceramide production and hepatic steatosis in diet-induced NAFLD mice." (PMID 37834101, 2023). "FASN is an attractive drug target in diabetes, cancer, fatty liver diseases, and viral infections." (PMID 37308485, 2023). "Hepatic steatosis is directly correlated with FASN expression." (PMID 35152538, 2022). "Furthermore, the mRNA levels of Kindlin-2 and the fatty acid synthase (Fas), an indicator of liver steatosis, were significantly increased in livers of HFD-fed mice, db/db, and ob/ob mice relative to those in their control mice." (PMID 35197460, 2022). "This in turn leads to increased FASN activity and hepatic steatosis." (PMID 36009446, 2022). "Moreover, the role of Hakai/FASN axis in other diseases such as fatty liver disease awaits to be elucidated." (PMID 36266428, 2022). "PTM could not only effectively prevent the development of NAFLD in mice with a low dosage, but alleviate the severity of liver steatosis, by inhibiting the expression of FASN and related metabolic genes." (PMID 35052685, 2021). "However, higher PTM concentrations (50 mg/kg) exhibited no obvious effects against NAFLD, resulting in only slightly reduced FASN levels and liver steatosis." (PMID 35052685, 2021). "Moreover, the O-GlcNAcylation of fatty acid synthase increases protein stability, promoting lipogenesis and hepatic steatosis." (PMID 34575972, 2021). "The NF-κB/MyD88 pathway drives inflammasome activation, which is a cytosolic regulator of inflammation that, through the caspase-2 pathway, activates SREBP1c to induce ACC-1 and FASN, contributing to the exacerbation of hepatic steatosis and inflammation in NAFLD." (PMID 34203484, 2021). "Furthermore, a model was employed to illustrate the roles of FASN and miR-30c-5pin hepatic steatosis." (PMID 28088781, 2017). "Furthermore, dietary PC reportedly alleviated orotic acid-induced fatty liver disease through suppression of liver fatty acid synthase activity." (PMID 26629827, 2015). "In addition, it has been shown to induce hepatic steatosis and increase fatty acid synthase expression in mice, corroborating to the idea of hepatic lipotoxicity in MS_deficient animals." (PMID 23614006, 2013). "In contrast, pharmacological inhibition of FASN in leptin receptor–deficient (db/db) mice ameliorated fed hyperglycemia, but not hepatic steatosis, in association with a reduction in food intake and BW gain, with these findings having cast doubt on the liver specificity of the drug action." (PMID 37681411, 2023).
Hepatic steatosis (continued). "Hepatic FASN deficiency may also alter lipid profiles and lipoprotein metabolism, and such effects may contribute to the fasting hypercholesterolemia apparent in ob/ob HKO mice and to the amelioration of hepatic steatosis in ob/ob HKO and Mc4r-KO HKO mice." (PMID 37681411, 2023). "In addition, nuciferine treatment significantly reversed the increase in hepatic levels of proteins SREBP-1c and fatty acid synthase (encoded by FASN) caused by the HFD, indicating that nuciferine can suppress the development of hepatic steatosis induced by an HFD." (PMID 36430146, 2022). "Furthermore, supplementing with selenium and magnesium inhibits the mRNA expression level of hepatic lipogenesis genes liver X receptor alpha (LXRα), SREBP-1c, and FASN (fatty acid synthase) to reduce the hepatic total cholesterol (TC) and attenuate liver steatosis in the rats fed by high-fat diet." (PMID 35624786, 2022). "Inhibition of the AMPK signaling pathway promotes hepatic steatosis, depending on the transcriptional and translational upregulation of lipogenic genes, such as those encoding sterol regulatory element-binding protein 1 (SREBP1) and fatty acid synthase (FASN) in hepatocytes." (PMID 36186461, 2022). "Thus, FASN is potentially a prominent factor determining the maximum liver capacity of fatty acid generation through liver lipid accumulation, a process which begins with simple liver steatosis and possibly progresses to inflammation." (PMID 33809508, 2021). "We found that miR-30c-5p was able to suppress FASN, the crucial enzyme in fatty acid biosynthesis and delivery of exogenous miR-30c-5p by rAAV was sufficient to attenuate triglyceride accumulation and liver steatosis in the db/db mice, suggesting a new therapeutic strategy against NAFLD." (PMID 28088781, 2017). "Additionally, mice supplemented with palmitoleic acid (C16:1, n-7) presented higher fat deposition, hepatic steatosis, and increased hepatic expression of sterol regulatory element-binding protein 1c and fatty acid synthase, demonstrating the pro-lipogenic effect of this MUFA." (PMID 29258511, 2017). "However, liver-selective FASN inhibition by platensimycin could lead to improved hepatic steatosis and T2DM in model mice." (PMID 23945333, 2013). "As expected, LG treatment significantly and dose-dependently ameliorated DXM-induced fatty liver and abrogated DXM-induced upregulation of FASN and CD36 protein expression." (PMID 39820544, 2025). "Our results suggest that the beneficial effects of LG on DXM-induced fatty liver are mediated, at least in part, by AMPK activation, which in turn downregulates FASN and CD36 expression." (PMID 39820544, 2025). "Inhibition of FAO contributes to hepatic steatosis, and enzymes regulating DNL, such as FASN, and FAO, such as ACOX1, play an important role in promoting MASH." (PMID 41448428, 2025). "FXR activation downregulates SREBP-1c and its lipogenic targets, including FASN, SCD1, and ACC, thereby reducing fatty acid synthesis and triglyceride accumulation and protecting against hepatic steatosis." (PMID 41438090, 2025). "ACC, FASN, PPARG, CIDEC, and especially CIDEA are all involved in the onset of hepatic steatosis and lipid droplet fusion in MASLD." (PMID 39958875, 2024). "In conclusion, the reduced levels of LPL, FASN, and SCD1 in liver and adipose tissue of IKKε knockout mice are in accordance with the observed lower lipid accumulation in serum and reduction of liver steatosis." (PMID 39409049, 2024). "The molecular mechanisms involved in the alcohol-induced fatty liver include crosstalk between the upregulation of SREBP-1c, ACC-1, and FASN and the downregulation of PPARα, which was evident in our reported data in the ALD group." (PMID 36959348, 2023). "Conversely, there is a decrease in fatty acid synthase (FASN) protein levels and de novo lipogenesis, leading to protection from diet-induced hepatic steatosis." (PMID 36978846, 2023).
Hepatic steatosis (continued). "For example, it was reported that ChREBP bound to ChoRE to upregulate the expression of FASN through the histone acetylation, methylation, and phosphorylation of histone H3 serine 10 (H3S10), promoting hepatic steatosis." (PMID 37834101, 2023). "gcn2−/− mice are protected against high-fat diet-induced hepatic steatosis by inhibiting lipogenesis and reducing oxidative stress, including srebp1c (sterol response element-binding protein 1c) and FASN (fatty acid synthase)." (PMID 36551306, 2022). "Since the effects of sucralose on hepatic steatosis were observed in mice, we then evaluated the levels of lipogenesis protein expressions in the liver, such as ChREBP, SREBP1, FASN, and ACC." (PMID 35685876, 2022). "On the other hand, the liver-specific deletion of PPAR-γ in db/db mice significantly improved hepatic steatosis, showing decreased expression of ACC, FASN, and SCD1." (PMID 35893906, 2022). "The expression analysis of hepatic steatosis-related genes showed that gallic acid treatment inhibits the expression of the ACACA and FASN genes in the liver." (PMID 34204038, 2021). "Conversely, glucocorticoids drive the expression of lipogenic genes including fatty-acid synthase (FASN) and acetyl-coA carboxylase 1 (Acaca), stimulate de novo lipogenesis, and block VLDL secretion, thus resulting in hepatic steatosis." (PMID 34067649, 2021). "HFD induced the expression of fatty acid synthase (FASN), an indicator of liver steatosis in both Nrf2 WT and KO mice." (PMID 33603948, 2021). "Nrf2 activation prevents metabolic dysregulation and insulin resistance in mice through the repression of hepatic enzymes such as FASN and ACC and protects against hypertriglyceridemia and fatty liver disease; this protection is abolished when Nrf2 is deleted." (PMID 34203484, 2021). "Earlier studies document that upregulated lipogenic gene expression, such as for fatty acid synthase (FASN) and acetyl-CoA carboxylase (ACACA), was resulting in increased SREBP-1c expression, which leads to hepatic steatosis." (PMID 33261004, 2020). "PG significantly reduced HFD-induced hepatic injury and hyperlipidemia, as well as hepatic steatosis via regulating phosphorylation of acetyl-CoA carboxylase (p-ACC) and expression of fatty acid synthase (FAS)." (PMID 32074961, 2020). "AMPK phosphorylation attenuated hepatic steatosis and fatty liver disease, etc., by inhibiting the expression of SREBP1, and further the inhibition of ACC and FASN." (PMID 31824338, 2019). "We show that all SHROB rats developed hepatic steatosis that was accompanied by enhanced expression of SREBP1, SREBP2, ACC1, and FASN proteins." (PMID 30201044, 2018). "SREBP-1c is a lipogenic transcription factor which upregulates acetyl-CoA carboxylase (ACC) and fatty acid synthase (FAS), which catalyze de novo fatty acid synthesis contributing to hepatic steatosis." (PMID 29358848, 2017). "Hepatic steatosis was also reduced by BBR and expression of fatty acid synthase (FAS) was inhibited in liver." (PMID 21304897, 2011). "Therefore, we aimed to test an alternative approach that blocks glucocorticoid-induced fatty liver without compromising its beneficial action, given the fact that upregulation of FASN and CD36 is crucial in mediating glucocorticoid-induced fatty liver." (PMID 39820544, 2025). "Based on these data, decreased serum PRL levels at ZT12 under SJL might inhibit hepatic CCND1 levels through MAPKs, leading to the activation of lipogenic enzymes (i.e., FASN and ACC) and hepatic steatosis." (PMID 40462123, 2025). "Taken together, we speculate that LG attenuates DXM-induced fatty liver, at least in part, by downregulating the expression of CD36 and FASN." (PMID 39820544, 2025). "Additionally, enhanced lipogenic SREBP‐1/FASN/ACC signaling at both transcriptional and translational levels, along with impaired fatty acid oxidation, further exaggerates hepatic steatosis." (PMID 40501499, 2025).